YTHDF1 (YTH N6-methyladenosine RNA binding protein F1)
Diseases named in the same sentence as YTHDF1 in open-access papers (continued):
Sharing a sentence is not in itself a finding about the gene and the disease.
tumor (continued). "We then investigated whether overexpression of USP14 could restore the delayed tumor progression phenotype in YTHDF1-deficient AGS and BGC-823 cells." (PMID 33791305, 2021). "Furthermore, in tumor immunity, the initiation of the immune response of T cells in YTHDF1-deficient mice is enhanced, featuring a stronger antitumour CD8+ T cell response." (PMID 33777035, 2021). "Therefore, YTHDF1 deficiency in DCs enhances antitumor immunity by promoting the cross-presentation of tumor antigens and cross-priming of CD8+ T cells, indicating that YTHDF1 is likely to become a promising antitumor target." (PMID 34869344, 2021). "Furthermore, the potential association between YTHDF1 expression and immune subtypes, molecular subtypes of different cancer types, promising immune biomarkers and tumor-infiltrating lymphocytes (TILs) in the TME was analyzed." (PMID 34026603, 2021). "Another research found that anti-tumour immunity in dendritic cells (DCs) was regulated by the m6A-binding protein YTHDF1, and the deficiency of YTHDF1 enhanced the cross-presentation of tumour antigens on DCs by decreasing the translation of lysosomal proteases in DCs36." (PMID 32934298, 2020). "Furthermore, statistical analysis of the 30 specimens revealed that YTHDF1 expression was associated with tumor depth (p = 0.014) and tumor size (p = 0.028)." (PMID 31131257, 2019). "In our study, YTHDF1 was highly expressed in ESCA tissues, and higher expression of YTHDF1 was associated with poorer survival, suggesting that YTHDF1 may act as a tumor-promoting gene in ESCC, but the specific tumor-promoting mechanism still needs further study." (PMID 36733344, 2023). "In a CRC-bearing mouse model, YTHDF1-deficient classical DCs presented a better therapeutic effect along with anti-PD-L1 treatment compared with that of the control mice by enhancing the ability of cross-presentation of tumor antigens of DCs and promoting the activation of T cells." (PMID 36960074, 2023). "However, YTHDF1 is potentially associated with multiple ferroptosis-related genes, which may affect the regulation of ferroptosis in tumor cells by affecting the expression of these genes." (PMID 35401696, 2022). "Our results indicated that Cluster 2, with high expression of ALKBH5 and low expression of YTHDF1, had more immune infiltration, immune checkpoint inhibitor expression, and tumor mutation burden than Cluster 1, hence suggesting that Cluster 2 might respond better to immunotherapy." (PMID 34079761, 2021). "And YTHDF1 promotes the degradation of neoantigens in dendritic cells by recognizing the m6A-modified transcripts encoding lysosomal protease, and blocks dendritic cells from delivering tumor neoantigens to T cells, allowing tumor cells to escape from immune surveillance." (PMID 34103054, 2021). "YTHDF1 was confirmed to induce the expression of lysosomal proteases by recognizing their m6A-marked mRNAs and increasing translation efficiency, which caused DCs to be unable constantly cross-present engulfed tumor neoantigens and then impeded the antigen-specific activation of CD8 + T cells." (PMID 35046996, 2021). "Compelling evidence has shown that multiple oncogenes relevant to PCa can be activated by YTHDF1 in an m6A-dependent manner, thereby enhancing tumor progression." (PMID 41252201, 2026). "Taken together, these observations indicate that the impact of m6A on tumor immunogenicity hinges less on overall mark abundance than on which reader or transcript lies downstream (e.g., YTHDF1–lysosome versus YTHDF2–NLRC5)." (PMID 41280938, 2025).
tumor (continued). "Using tumor samples collected from the Lgr5-specific Ythdf1cki mouse model, qPCR analysis revealed that YTHDF1 knock-in increased the expression of NOTCH1 downstream targets, including MAML1, MAML2, HES1, and HEY1." (PMID 41423446, 2025). "YTHDF1 promoted m6A-dependent self-renewal in CSCs and patient-derived organoids and increased the tumor-initiating potential in vivo." (PMID 41423446, 2025). "Ythdf1 depletion significantly suppressed tumor growth and decreased tumor weight and volume compared with the immunodeficient NSG mouse model." (PMID 39587835, 2025). "The YTHDF1 reading protein is responsible for the regulation of lysosomal proteases and the facilitation of tumor immune escape." (PMID 39904996, 2025). "The innovation of this study is complementary to the study of YTHDF1 for GC apoptosis, which found that it not only promotes tumor growth but also inhibits cell apoptosis." (PMID 39821576, 2025). "Numerous reports have highlighted the differential expression and functional roles of YTHDF1 in tumor development." (PMID 39821576, 2025). "YTHDF1 upregulation increases PD‐L1 expression, diminishing T cell cytotoxicity and ferroptosis; this effect affirms YTHDF1’s critical role in tumor immune evasion." (PMID 39802639, 2025). "The findings demonstrated a positive correlation between the expression level of YTHDF1 and lymph node metastasis, as well as the expression of PD‐1 and PD‐L1 in the tumor tissues of GC patients." (PMID 39821576, 2025). "An exosome-mediated CRISPR/Cas9 delivery system has been developed to achieve in vivo YTHDF1 knockout, yielding potent anti-tumor effects." (PMID 41403953, 2025). "As an m6A reader that facilitates mRNA translation, YTHDF1 serves as a crucial regulator in tumor progression." (PMID 40278596, 2025). "The significance of YTHDF1 lies in its specificity for CSCs, which are increasingly recognized as the primary mediators of tumor initiation, metastasis, and relapse in CRC." (PMID 41423446, 2025). "YTHDF1 deficiency curtails this pathway, reducing lysosomal gene translation, which preserves MHC‐I and antigen integrity, converting immunologically cold tumours into responsive hot tumours." (PMID 40673641, 2025). "The xenograft tumor phenotype was further evidenced by a reduction in tumor volume after YTHDF1 knockdown, alongside a significant decrease in the Ki67 staining positive rate, as determined by immunohistochemistry (IHC) staining." (PMID 40251202, 2025). "YTHDF1 deficiency has been shown to restore the proteolysis of MHC-I molecules and their associated antigens, thereby enhancing tumor immune surveillance." (PMID 40739089, 2025). "Strikingly, YTHDF1 silencing, when combined with anti-PD-1 therapy, significantly suppresses tumor progression." (PMID 40034695, 2025). "After confirming that YTHDF1 promotes tumor cell proliferation in vitro, we evaluated its effect in vivo." (PMID 40251202, 2025). "We created YTHDF1 knockdown cell lines in DU145 and 22RV-1, demonstrating that YTHDF1 knockdown markedly reduced tumor cell proliferation." (PMID 40251202, 2025). "For DC, downregulation of YTHDF1 promotes cross-cross-presentation of tumor antigens and cross-initiation of antigen-specific T cells." (PMID 40061211, 2025). "Tumor-intrinsic YTHDF1 also promotes lysosomal gene translation, thereby accelerating MHC-I antigen degradation and impairing immune surveillance." (PMID 41403953, 2025). "The depletion of YTHDF1 suppresses tumor growth by promoting CD8+ T cell infiltration, and this effect increases when combined with PD‐1 blockade." (PMID 39802639, 2025). "YTHDF1 influences tumor antigen cross-presentation in dendritic cells and the cross-priming of CD8+ T cells, whereas its knockdown boosts the antitumor activity of specific CD8+ T cell populations." (PMID 40251202, 2025). "Our combination approach of YTHDF1 inhibition plus chemotherapies synergistically suppressed tumor growth, highlighting its potential for CRC treatment." (PMID 41423446, 2025).
tumor (continued). "In contrast, YTHDF1 has an anti-tumor effect on ocular melanoma by promoting the translation of m 6A-modified mRNA of HINT2 which is a tumor suppressor." (PMID 40483535, 2025). "Targeting YTHDF1 with nanoparticle-delivered siRNA or a selective pharmacological inhibitor promoted chemosensitivity in xenograft tumor models established from colorectal CSCs." (PMID 41423446, 2025). "Loss or inhibition of YTHDF1 disrupted NOTCH1 translation, induced DNA damage, and thus synergized with commonly used chemotherapies in CRC, 5-FU and Oxaliplatin, to potentiate tumor eradication in vivo." (PMID 41423446, 2025). "YTHDF1 has emerged as a critical factor in both tumor‐intrinsic and microenvironment‐related processes." (PMID 39587835, 2025). "Through its translational regulation of these key immune molecules, YTHDF1 plays a central role in promoting immune evasion and tumor progression." (PMID 39911396, 2025). "Functionally, Ythdf1 deletion suppresses GC cell proliferation and colony formation in vitro, and induces complete tumor regression in immunocompetent mice." (PMID 41403953, 2025). "Elevated YTHDF1 expression has been documented in multiple cancers and is tied to enhanced cell proliferation, migration, and tumor aggressiveness." (PMID 41472023, 2025). "These regulators drive tumor progression and influence immune infiltration, with YTHDF1 promoting Treg infiltration, potentially suppressing Anti-tumor immunity." (PMID 41029427, 2025). "This study further revealed that YTHDF1 promotes USP14 protein translation in an M6A-dependent manner and that overexpression of USP14 can counteract the tumor-suppressive effects of YTHDF1 knockdown in GC cells." (PMID 41312360, 2025). "Our study revealed that YTHDF1 knockdown inhibits tumor cell proliferation, migration, and xenograft tumor formation by decreasing p27 protein stability through proteasome degradation signaling." (PMID 40251202, 2025). "The enhanced cancer immunity induced by Ythdf1 depletion was partially due to the enhanced Ifn‐γ signaling because inhibition of Ifn‐γ with blocking antibody increased the tumor growth in Ythdf1 knockdown cells." (PMID 39587835, 2025). "Concurrently, experiments applying xenograft tumor formation in nude mice showed that the knockdown of YTHDF1 markedly retarded tumor growth in vivo." (PMID 40251202, 2025). "In melanoma and colorectal cancer, the m6A reader YTHDF1 reduces the ability of DCs to present tumor neoantigens to T cells." (PMID 40176140, 2025). "In Cohort IV, which included paired CRC tumor and adjacent normal tissues (N = 12), we consistently found positive correlations between the protein expression of YTHDF1 and that of CD133 and LGR5." (PMID 41423446, 2025). "The increased translation of PD-L1 and other immunosuppressive factors driven by YTHDF1 contributes to the establishment of an immune-resistant environment, hindering effective anti-tumor immune responses." (PMID 39911396, 2025). "YTHDF1 further suppresses anti-tumor immunity by regulating antigen presentation in dendritic cells (DCs)." (PMID 41403953, 2025). "An exosome-mediated CRISPR/Cas9 delivery system was designed to target the oncogenic YTHDF1 gene in vivo, with the goal of depleting YTHDF1 to mitigate tumor progression by restoring antitumor immunity." (PMID 40958857, 2025). "In contrast, CSC28 and POP66 cells with YTHDF1 knockdown had impaired tumor-initiating potential and reduced stem cell frequency." (PMID 41423446, 2025). "YTHDF1 reduction enhances the capacity of DCs to present tumor antigen by decreasing its antigen consumption." (PMID 39904996, 2025). "YTHDF1 in dendritic cells enhances the translation of genes involved in antigen processing and presentation, thereby influencing T-cell activation and tumor immunogenicity." (PMID 41403953, 2025). "The modulation of YTHDF1 can reinstate the anti-tumor immune response, while targeting ADAR1 offers a novel approach for cancer treatment." (PMID 41446042, 2025).
tumor (continued). "In dendritic cells, RT induces YTHDF1, which enhances cathepsin translation and accelerates lysosomal degradation of activated STING complexes; DC-specific Ythdf1 loss boosts IFN-I, cross-priming, and tumor control after RT or radio-immunotherapy." (PMID 41280938, 2025). "Nevertheless, the critical YTHDF1 downstream m6A-modified factor regulating tumor progression is likely modulated by the tumor microenvironment and genomic landscape." (PMID 40251202, 2025). "The reduction of YTHDF1 impedes tumor growth by reinstating CD8+ T cell infiltration, suggesting its significant role in programmed cell death." (PMID 39802639, 2025). "YTHDF1 promotes the growth of tumor cells in LUAD by enhancing the expression of proteins in the cell cycle and affects the prognosis and stage of tumors." (PMID 39033180, 2024). "For example, the depletion of MRD or the m6A-specific binding protein YTHDF1 inhibits tumor growth by restoring CD8+ T-cell infiltration and, when combined with PD-1 blockade, this results in improved tumor control." (PMID 39759516, 2024). "We verified that IR indeed increased YTHDF1 expression in tumor-infiltrating DCs at both mRNA and protein levels." (PMID 39325547, 2024). "A recent study reveals that EBV EBNA1 promotes the degradation of the METTL3 protein via the K48-linked ubiquitin pathway, decreasing TLR9 m6A modification and YTHDF1-enhanced translation, thus promoting tumor immune evasion." (PMID 39695216, 2024). "In CRC, YTHDF1 impairs anti‐tumour immunity by negatively regulating CD8+ T cell infiltration while upregulating CXCL1 to promote MDSCs infiltration." (PMID 38545841, 2024). "In HCC, YTHDF1 binds to mRNA to enhance the expression of autophagy-related genes and increase the possibility of tumorigenesis, while knockdown of YTHDF1 inhibits autophagy and delays tumor progression." (PMID 39033180, 2024). "YTHDF1 influences antigen degradation, thereby restricting DCs’ capacity to present tumor neoantigens and modulating their response to PD-L1 inhibitors." (PMID 39199429, 2024). "Despite the known impact of YTHDF1 on tumor cells, its role in the tumor microenvironment (TME) is less well-documented." (PMID 38898486, 2024). "Studies have shown that m6A negatively regulates tumor neoantigen-specific immunity through YTHDF1, and YTHDF1 cross-presents tumor antigens in DCs, thereby stimulating T cell activation." (PMID 39072324, 2024). "YTHDF1 recognizes m6A modification of JAK1 mRNA in Tumor-infiltrating myeloid cells mediated by METTL3, and METTL3-m6A-YTHDF1 enhances the translation of JAK1 mRNA, subsequently promoting STAT3 phosphorylation and tumor growth in mice." (PMID 39726589, 2024). "For instance, YTHDF1 inhibits the presentation of tumor neoantigens to T cells by recognizing m6A modification in dendritic cells, leading to tumor cell evasion from immune surveillance." (PMID 39372951, 2024). "Elevated YTHDF1 levels are associated with increased NOTCH1 expression, a tumor stem cell marker, and enhanced HCC stemness, which can lead to drug resistance." (PMID 38898486, 2024). "The m6A site on the MCT1 transcript targeting by YTHDF1 shows the significance of post-transcriptional control in tumor lactate accumulation." (PMID 39557826, 2024). "An IFN-γ–based ELISPOT assay showed that CD8+ T cells isolated from Ythdf1-cKO+IR tumor–bearing mice had a greater number of IFN-γ+ spots than did those isolated from WT+IR mice." (PMID 39325547, 2024). "Tumour weights were increased in YTHDF1 overexpression group than in Vector group (p = 0.0001), and decreased in shYTHDF1‐1 (p < 0.0001) and shYTHDF1‐2 group (p < 0.0001) than in shControl group." (PMID 38683130, 2024). "This research indicates that YTHDF1‐driven MDSC accumulation suppressive anti‐tumour immune cells, promoting immune evasion in CRC." (PMID 39135292, 2024).
tumor (continued). "Our results show that most of the genes are negatively correlated with these drugs (based on IC50 values) between high- and low-risk groups in each tumor except for RBFOX2 in some tumors, YTHDF1 in SKCM and LUAD, FTO in LUSC and TGCT, and FMR1 in OV and UCS." (PMID 39457524, 2024). "Several experiments have validated that the inhibition of YTHDF1 and cisplatin synergistically perform tumor‐suppressive functions." (PMID 38721006, 2024). "Studies have shown that RUVBL1/2 interferes with the RNA binding activity of YTHDF1, reducing the translation of cancer-related genes and inhibiting tumor cell proliferation and invasion, demonstrating significant antitumor effects in CRC." (PMID 39295872, 2024). "Li's group discovered that YTHDF1 deletion or a methionine‐restricted diet combined with PD‐1 inhibition can effectively suppress tumour growth by reestablishing CD8+ T cell infiltration." (PMID 39135292, 2024). "In summary, our paper elucidated that knocking down KIAA1429 can reduce FOXM1 expression through YTHDF1-mediated m6A modification, thereby inhibiting MM aerobic glycolysis and inhibiting tumor development." (PMID 39060874, 2024). "Other studies have shown that YTHDF1 plays an important role in cancer development and long-lasting, novel, antigen-specific anti-tumor immunity." (PMID 38339157, 2024). "Blocking YTHDF1 can reactivate the suppressed anti-tumor immunity and synergistically improve the therapeutic effect of anti-PD-L1 inhibitors." (PMID 38339157, 2024). "Our results demonstrated that when YTHDF1 was depleted, both the cross-presentation and priming function of DCs were significantly enhanced, which led to superior tumor control in the context of IR." (PMID 39325547, 2024). "A recent study showed that inhibition of YTHDF1 expression delayed tumor progression by increasing CD8+ T cell content or in combination with the use of anti-PD-1 drugs." (PMID 39033180, 2024). "YTHDF1 impairs anti‐tumour immunity via an m6A‐p65‐CXCL1/CXCR2 axis and serves as a therapeutic target for ICB in colorectal cancer." (PMID 39568154, 2024). "Similar observations were made in mice with the CT26 tumor model, which is insensitive to PD-1 therapy; the deletion of YTHDF1 in CT26 cells followed by anti-PD-1 treatment markedly inhibited tumor growth." (PMID 39372415, 2024). "YTHDF1 promotes glycolysis by up-regulating the expression level of mRNA, thereby accelerating tumor progression." (PMID 39033180, 2024). "designed an exosome‐mediated CRISPR/Cas9 plasmid DNA to target oncogenic YTHDF1 in vivo, contributing to YTHDF1 depletion and anti‐tumour activity." (PMID 39135292, 2024). "Our results demonstrated that IR increased the expression of cathepsins A and B in B16-OZ tumor–infiltrating DCs, which was abolished in Ythdf1-deleted DCs." (PMID 39325547, 2024). "YTHDF1 deletion in dendritic cells was previously found to improve anti-tumor immunity and slow tumor development in a mouse model." (PMID 38339157, 2024). "By analyzing tumor-infiltrating DCs grown in WT or Ifnar1-KO mice, we demonstrated that IFNAR deficiency completely abolished IR induction of YTHDF1 expression observed in tumors of WT animals." (PMID 39325547, 2024). "YTHDF1 recognizes and binds to m6A-modified RNA, regulating the translation of various cancer-related genes and playing crucial roles in tumor initiation, progression, and therapeutic resistance." (PMID 39295872, 2024). "Targeting YTHDF1 enhances the anti-tumor immune response and increases the effectiveness of anti-PD-1 therapy, providing a potential novel strategy for the treatment of colorectal cancer." (PMID 39759516, 2024). "Blocking the STING-suppressive functions of YTHDF1 and HO-1, respectively, improved antitumor T cell immunity and tumor control after RT." (PMID 39621308, 2024). "As an m6A reader, YTHDF1 is up‐regulated in tumour tissues and related to poor prognosis of various tumours." (PMID 38444279, 2024).